TM9SF2 (transmembrane 9 superfamily member 2)
Description:
In the intracellular compartments, may function as a channel or small molecule transporter.
Synonyms: P76; Lnc-PCIR
Tractability: Antibody: UniProt places it where antibodies can reach, with high confidence; its Gene Ontology location is reachable by antibodies, with high confidence; UniProt predicts a signal peptide or a membrane-spanning region. PROTAC: ubiquitination databases record sites on it; its protein half-life has been measured.
Gene: Protein-coding gene on chromosome 13 (99,446,311 to 99,564,048, forward strand). Ensembl gene ENSG00000125304.
Subcellular location: Endosome membrane; Golgi outpost; Cytoplasm, cytoskeleton, microtubule organizing center
Gene Ontology:
Biological process: ceramide metabolic process; glycosphingolipid biosynthetic process; regulation of heparan sulfate proteoglycan biosynthetic process; protein localization to membrane
Cellular component: extracellular exosome; Golgi apparatus; endosome; membrane; plasma membrane; postsynaptic Golgi apparatus; cytoplasm; endosome membrane; microtubule organizing center
Genetic constraint (gnomAD): Loss-of-function variants: 9 observed, 61.45 expected, observed/expected ratio (o/e) 0.15, 90% interval 0.087 to 0.26. The upper end of that interval is the gene's LOEUF score, 0.26, which puts it in group 1 of 6, group 1 being the genes least tolerant of losing a copy. Missense variants: 471 observed, 710.64 expected, observed/expected ratio (o/e) 0.66, 90% interval 0.61 to 0.71. Synonymous variants: 233 observed, 253.82 expected, observed/expected ratio (o/e) 0.92, 90% interval 0.82 to 1.02.
Homologues: Orthologues: chimpanzee TM9SF2 (100% identical), macaque TM9SF2 (99% identical), guinea pig TM9SF2 (97% identical), pig TM9SF2 (97% identical), dog TM9SF2 (97% identical), mouse Tm9sf2 (96% identical), rat Tm9sf2 (93% identical), rabbit TM9SF2 (92% identical), tropical clawed frog tm9sf2 (86% identical), zebrafish tm9sf2 (83% identical), Drosophila melanogaster TM9SF2 (67% identical). Paralogues in human: TM9SF4 (43% identical), TM9SF3 (29% identical), TM9SF1 (28% identical).
Diseases named in the same sentence as TM9SF2 in open-access papers:
TM9SF2 is named in the same sentence as 23 diseases in open-access papers, as found by Europe PMC text mining. Sharing a sentence is not in itself a finding about the gene and the disease. The quoted sentences say what the papers report.
colorectal cancer (8 papers, 2018 to 2025). A primary or metastatic malignant neoplasm that affects the colon or rectum. "TM9SF2 is highly expressed in colorectal cancer and is associated with tumor invasion, metastasis, and poor prognosis." (PMID 41315466, 2025). "TM9SF2 may regulate the biosynthesis of glycosphingolipids by regulates the subcellular localization of globotriaosylceramide synthase.TM9SF2 may be an oncogene and a prognostic marker with high expression associated with poor prognostic in pancreatic adenocarcinoma and colorectal cancer." (PMID 38735008, 2024). "Transmembrane 9 superfamily member 2 (TM9SF2) is a transmembrane protein that has been identified as a novel oncogene in colorectal cancer." (PMID 39475897, 2024). "TM9SF2 is an evolutionarily conserved transmembrane protein and has been identified as a glycolipid-regulating factor and a novel colorectal cancer oncogene." (PMID 31541081, 2019). "For our second approach, we evaluated the mRNA levels of TM9SF2 in a panel of nine commonly used colorectal cancer cell lines using qRT-PCR." (PMID 30333512, 2018). "Approximately one-third of colorectal cancer patients show overexpression of TM9SF2 mRNA, which may be regulated by the Ets family transcription factor ELF1." (PMID 39475897, 2024). "TM9SF2 was recently identified as a potential oncogene in colorectal cancer through transposon mutagenesis in mouse models and found to be overexpressed in many human colorectal cancer samples." (PMID 33803852, 2021). "Interestingly, a recent genome-wide CRISPR-Cas9 screen, carried out by incubating EHEC with human colorectal carcinoma cell line HT-29, also identified LAPTM4A and TM9SF2 as key factors for EHEC toxicity to cells." (PMID 30481169, 2018).
pancreatic adenocarcinoma (3 papers, 2019 to 2024). "Another study found that EIF4A3 is recruited by LINC01232 to stabilize transmembrane 9 superfamily member 2 (TM9SF2) mRNA and regulate its expression, thereby contributing to pancreatic adenocarcinoma (PAAD)." (PMID 34458150, 2021).
pancreatic cancer (2 papers, 2019 to 2023). "Based on TCGA data, the upregulation of TM9SF2 expression was observed in pancreatic cancer tissues." (PMID 31541081, 2019). "Rescue experiments were performed to explore whether LINC01232 affected the tumorigenesis and development of pancreatic cancer by TM9SF2." (PMID 31541081, 2019). "In pancreatic cancer, LINC01232 modulates TM9SF2 mRNA stability via recruiting EIF4A3." (PMID 37940881, 2023).
AIDS (1 paper, 2015). A syndrome resulting from the acquired deficiency of cellular immunity caused by the human immunodeficiency virus (HIV). "Several SNPs in the region of TM9SF2 showed signs of association with human AIDS progression in vivo." (PMID 25884674, 2015).
cerebrovascular diseases (1 paper, 2024). "Although research on TM9SF2 in cerebrovascular diseases and sleep disorders is currently lacking, our findings suggest it could serve as a promising diagnostic and therapeutic target in these fields." (PMID 39475897, 2024).
depression (1 paper, 2024). "A multi-omics study links TM9SF2 to early-onset severe depression and shows a strong positive correlation with glutamine." (PMID 39475897, 2024).
gastric cancer (1 paper, 2018). A primary or metastatic malignant neoplasm involving the stomach. "Mining the CCGD database revealed that Tm9sf2 was a transposon-targeted mutation in an additional eight forward genetic screens, including screens for liver, pancreatic, breast, and gastric cancer." (PMID 30333512, 2018).
influenza (1 paper, 2021). An acute viral infection of the respiratory tract, occurring in isolated cases, in epidemics, or in pandemics; it is caused by serologically different strains of viruses (influenzaviruses) designated A, B, and C, has a 3-day incubation period, and usually lasts for 3 to 10 days. "In addition to B4GALNT2, this CRISPR/Cas9 activation screen identified two other potential influenza inhibitors: the transmembrane 9 superfamily member 2 (TM9SF2) and Ras Additionally, Rab Interactor 2 (RIN2)." (PMID 33810083, 2021).
intestinal tumors (1 paper, 2018). "This analysis indicates TM9SF2 has a contributing role in the formation of murine intestinal tumors." (PMID 30333512, 2018).
periodontitis (1 paper, 2023). An acute or chronic inflammatory process that affects the tissues that surround and support the teeth. "It is quite conceivable that results from research on Transmembrane 9 superfamily member 2 as a new oncogene can also be applied to the therapy of periodontitis." (PMID 36979679, 2023).
preeclampsia (1 paper, 2021). Preeclampsia is a hypertensive disorder of pregnancy that is characterized by new-onset hypertension with proteinuria presenting after 20 weeks of gestation, and depending on mild or severe forms may initially present with severe headache, visual disturbances, and hyperreflexia. "In this study hESF also had altered production of factors previously identified to be increased in the decidua of women with preeclampsia, including COL4A1, LNPEP, TM9SF2 and COTL1." (PMID 33898438, 2021).
stomach tumors (1 paper, 2018). "Mining of the SBCDDB revealed that Tm9sf2 was a common insertion site in 7.2% (121/1674 tumors) of all digestive tumors, which includes liver, pancreas, intestine, and stomach tumors, but was not identified as a driver in hematopoietic tumors." (PMID 30333512, 2018).
cancer (5 papers, 2018 to 2024). A tumor composed of atypical neoplastic, often pleomorphic cells that invade other tissues. "Overexpression of ERBB3, EZR, and TM9SF2 has been associated with cancer progression, increased proliferation and metastasis or poor survival." (PMID 33690729, 2021). "Analysis of data from our previous SB transposon forward genetic screen identified Tm9sf2 as a top candidate cancer gene." (PMID 30333512, 2018). "We found that TM9SF2 expression correlates with disease severity with late stage (III & IV) cancers having a significantly higher level of expression compared to stage I." (PMID 30333512, 2018). "To further explore the role of TM9SF2 as a cancer gene, we used two publicly available databases that catalog cancer genes discovered using DNA transposon insertional mutagenesis." (PMID 30333512, 2018). "Of these 77 candidate cancer genes, we chose to focus on TM9SF2 for further study because we found this gene to be overexpressed in a large percentage of human CRC samples, suggesting a potential oncogenic function." (PMID 30333512, 2018). "Mining of other publicly available SB transposon databases revealed further support for Tm9sf2 as a candidate cancer gene." (PMID 30333512, 2018). "RNAi silencing of TM9SF2 reduced CRC cell growth in an anchorage-independent manner, a hallmark of cancer." (PMID 30333512, 2018). "In addition to the enrichment of guides targeting TM9SF2, LAPTM4A, and genes related to sphingolipid biosynthesis, our analysis detected enrichment for guides targeting several genes associated with cancer and cell proliferation (MLLT3, TFAP4, ZNF217, and DUSP6) (35, –, 38)." (PMID 29921669, 2018). "This suggests the difference of the role of the same gene in different cancer type and large clinical samples are needed to confirm the role of G3BP2 and TM9SF2 in ccRCC." (PMID 38735008, 2024).
tumor (3 papers, 2018 to 2025). "We found that tumors derived from the endometrium contained the highest rate of TM9SF2 mutation at a tumor frequency of approximately 2% (13/656 total tested)." (PMID 30333512, 2018). "This reduced tumor burden corresponded to a significantly increased overall survival for mice bearing TM9SF2 knockout tumor cells." (PMID 30333512, 2018). "In all but eight samples the levels of TM9SF2 mRNA were increased in the patient’s tumor sample compared to the matched normal sample." (PMID 30333512, 2018). "We used RNAi and CRISPR/Cas9 to either reduce or knockout the expression of TM9SF2, which had the effect of reducing tumor fitness in both the in vitro and in vivo settings." (PMID 30333512, 2018). "In our screen the T2/Onc transposon insertions were mapped to the murine Tm9sf2 gene in nine tumor samples." (PMID 30333512, 2018). "To determine if TM9SF2 knockout has an effect on tumor growth in vivo we performed a xenograft experiment using HT-29 TM9SF2 KO cells compared to parental cells." (PMID 30333512, 2018). "Furthermore, CRISPR/Cas9 knockout of TM9SF2 substantially diminished CRC tumor fitness in vitro and in vivo." (PMID 30333512, 2018). "Analyses of gene expression levels using microarray or RNA sequencing reveal that, when compared to the mean expression distribution of tumor samples that are diploid for TM9SF2, TM9SF2 is overexpressed in approximately one-third (194/601 tumors) of large intestine tumors." (PMID 30333512, 2018). "Finally, using RNAi and CRISPR/Cas9 gene editing we demonstrated that reduction or complete knockout of TM9SF2 resulted in reduced tumor fitness in the in vitro and in vivo settings." (PMID 30333512, 2018).
infection (2 papers, 2018 to 2019). The state of being infected such as from the introduction of a foreign agent such as serum, vaccine, antigenic substance or organism. "To gain greater insight into the mechanism by which TM9SF2 and LAPTM4A enable infection by EHEC, we determined their subcellular localization in HeLa cells via confocal microscopy." (PMID 29921669, 2018). "Intriguingly, the TM9SF2 and LAPTM4A mutants were also significantly more abundant than wt cells by 5 days post-ΔescN mutant infection, suggesting that these factors not only contribute to resistance to T3SS-mediated cytotoxicity, but also could be host factors facilitating intoxication." (PMID 29921669, 2018).
TM9SF2 also shares sentences with these, for which no sentence is quoted: breast carcinoma (1 paper); digestive tumors (1); glioma (1); Hyperinsulinemia (1); leukaemia (1); lymphoma (1); osteoarthritis (1); sleep disorder (1).